ENSG00000288000 (novel protein)
Gene: Protein-coding gene on chromosome 20 (43,458,054 to 43,541,881, forward strand). Ensembl gene ENSG00000288000.
Genetic constraint (gnomAD): Loss-of-function variants: 75 observed, 125.42 expected, observed/expected ratio (o/e) 0.6, 90% interval 0.5 to 0.73. Missense variants: 1,279 observed, 1,447.3 expected, observed/expected ratio (o/e) 0.88, 90% interval 0.84 to 0.93. Synonymous variants: 597 observed, 545.54 expected, observed/expected ratio (o/e) 1.09, 90% interval 1.02 to 1.17.